TACC3 (transforming acidic coiled-coil containing protein 3)
Diseases named in the same sentence as TACC3 in open-access papers (continued):
Sharing a sentence is not in itself a finding about the gene and the disease.
tumor (continued). "TACC3 expression in poorly differentiated tumors tumor was remarkably higher than that in well differentiated tumors,which was consistent with the TCGA data." (PMID 34134633, 2021). "Here, TIMER-based analysis was used to determine the correlation between TACC3 expression and levels of tumor infiltrating immune cells in KIRC." (PMID 33714201, 2021). "To further investigate the upregulation of TACC3, we performed a data analysis of public data sets, which indicated that TACC3 expression was significantly elevated in tumor samples compared with their normal counterparts." (PMID 29358577, 2018). "While TACC3 was highly expressed in 94/136 cases (69.1%), the expression of TACC3 was recognized in the cytoplasm of tumor cells in all cases." (PMID 29135996, 2017). "No significant heterogeneity was observed, pooled estimates of 3 literatures showed that upregulated TACC3 expression was closely related to tumor differentiation (poorly versus well/moderately OR=1.90, 95% CI=1.25–2.88, P=0.003, I2= 0, Ph=0.557)." (PMID 29088887, 2017). "Functional annotations indicated that high TACC3 expression was tightly connected with tumor proliferation, DNA repair, stem properties, EMT and several other malignant biological processes." (PMID 28273854, 2017). "The consequences of this for tumour progression are unclear, but development of a therapeutic agent that inhibits signalling and prevents TACC3 removal is most likely to bring FT3-positive cells back to a normal state." (PMID 28855393, 2017). "Meanwhile, TACC3 participated in the repair of DNA damage, protecting tumor cells from entering into apoptosis or other cell deaths." (PMID 28273854, 2017). "We found that targeted silencing of TACC3 markedly inhibited xenograft tumor growth and the formation of pulmonary metastatic nodes, suggesting that down-regulation of TACC3 suppresses EMT-induced invasion and metastasis." (PMID 27705912, 2016). "As a result, 77 (47.8%) tumour samples had high TACC3 expression, and 84 (52.2%) tumour samples had low TACC3 expression." (PMID 27248823, 2016). "The expression of TACC3 in CCA tissues was higher than in the paired adjacent non-tumor tissues (P=0.008)." (PMID 27705912, 2016). "Tumours with an immunoreactivity score (IRS) exceeding 5 were classified as having high TACC3 expression." (PMID 27248823, 2016). "We found that TACC3 expression was higher in CCA tissues than in adjacent non-tumor tissues at both the mRNA and protein levels (P<0.05)." (PMID 27705912, 2016). "Based on our interesting in vitro findings, we next established subcutaneous and pulmonary metastasis tumor models to further investigate the potential therapeutic role of TACC3 in CCA, in vivo." (PMID 27705912, 2016). "According to the multivariate analysis, TACC3 expression (HR = 2.267, P < 0.001), tumor size (HR = 2.358, p = 0.003), microvascular invasion (HR = 2.527, p < 0.001), and TNM staging (HR = 1.272, P = 0.035) were independent predictors of survival." (PMID 26219398, 2015). "TACC3 knockdown suppressed tumor stem cell-like characteristics through the Wnt/β-catenin and PI3K/AKT signaling pathways." (PMID 26219398, 2015). "The protein expression of TACC3 in the tumor tissues was mostly higher than those paired adjacent normal samples." (PMID 25760075, 2015). "TACC3 protein was expressed predominantly in the plasma membrane of HCC cells in the tumor regions (T), whereas TACC3 was only occasionally expressed in the liver cells of the adjacent non-cancerous tissue (N)." (PMID 26219398, 2015). "We observed the up-regulation of S100A11 protein which functions in tubulin polymerization, motility, and tumor invasion and down-regulation of the transforming acidic coiled-coil-containing protein 3 (TACC3)." (PMID 24628760, 2014). "The FGFR2 fusion partner observed in this patient's tumor, TACC3, is overexpressed in many tumor types with enhanced cell proliferation, migration, and transformation observed in cells overexpressing TACC3." (PMID 24550739, 2014).
tumor (continued). "A significant difference in TACC3 expression between tumor types was noted, with TACC3 being expressed less frequently in serous papillary tumors than clear cell tumors (Fisher's exact test, p = 0.0113)." (PMID 15918899, 2005). "Additionally, single-sample GSEA (ssGSEA) scores for glycolysis positively correlated with TACC3 expression in BC cell lines and tumor samples." (PMID 40246827, 2025). "Given the compartmentalized nature of tumor-immune interactions, we hypothesized that TACC3 regulates PUFA secretion into the TIME." (PMID 40866361, 2025). "This case highlights the potential radiological characteristics of diffuse gliomas with FGFR3::TACC3 fusion, particularly the presence of coarse calcifications, that may serve as notable imaging features of this tumor." (PMID 40417325, 2025). "Furthermore, we demonstrated that silencing tumor-derived TACC3 optimizes the cytotoxicity of infiltrating CD8+ T lymphocytes." (PMID 40866361, 2025). "Predicting TACC3 expression through radiomic features may provide valuable insights into tumor biology and aid clinical decision-making." (PMID 39603208, 2025). "Pharmacological inhibition of glycolysis abrogates TACC3-driven tumor growth in vitro and in vivo." (PMID 40246827, 2025). "Moreover, mIHC analysis of six HCC patient samples revealed that the levels of CD8+ T-cell infiltration and GZMB secretion were strikingly greater in TACC3-low tumor samples than in TACC3-high tumor samples." (PMID 40866361, 2025). "Next, flow cytometry analysis of tumor tissues from an in situ HCC model revealed that interference with TACC3 expression in Hepa1‒6 cells increased the ratio of total tumor-infiltrating CD8+ T cells and IFN-γ+CD8+ T cells while clearly decreasing the proportion of PD-1+CD8+ T cells." (PMID 40866361, 2025). "To explore whether TACC3 also supports and promotes PDAC progression in vivo, we constructed a subcutaneous tumor model with Panc-1 cells in mice and regulated TACC3 gene expression via the doxycycline (DOX)-inducible Tet-On system." (PMID 38012214, 2023). "In addition, the combination of TACC3 knockdown plus gemcitabine chemotherapy further inhibited the tumor progression." (PMID 38012214, 2023). "In addition, we constructed a subcutaneous tumor model to explore the combination effect of TACC3 knockdown plus gemcitabine chemotherapy." (PMID 38012214, 2023). "IF staining of previously obtained frozen sections of subcutaneous tumor tissue also showed that knockdown of the TACC3 protein under in vivo conditions interfered with normal spindle assembly in Panc-1 cells, with a marked increase in cells with abnormal spindle morphology." (PMID 38012214, 2023). "It was further illustrated that TACC3 might influence tumor immunogenicity and become a possible biomarker for forecasting the prognosis of tumors." (PMID 35855850, 2022). "Significantly lower methylation levels of PTTG1 and TACC3 promoters were found in tumor tissues compared with normal tissues, which may account for the abnormal expression of the signature genes in LUAD." (PMID 34869385, 2021). "In addition, we proceeded to study the correlation between TACC3 expression and the tumor immune infiltration and T cell exhaustion in KIRC." (PMID 33714201, 2021). "In that context, a non-viral delivery system, such as nanoparticles, could be a new and safe way to transfer a TACC3 inhibitor or siRNA to tumor cells in combination with traditional CRT." (PMID 30341253, 2018). "More recently, the oncogenic effects exerted by TACC3 during tumor progression have become clearer." (PMID 29358577, 2018). "In general, these data indicated that TACC3 is strongly related to tumor progression." (PMID 29358577, 2018).
tumor (continued). "The depletion of TACC3 has been shown to suppress tumor growth without damaging normal tissues, cause premature senescence of tumor cells, and increase the susceptibility of tumor cells to paclitaxel (which disrupts the microtubule network)." (PMID 29135996, 2017). "Additionally, the pooled odds ratios (ORs) showed that increased TACC3 expression was also related to positive lymph node metastasis (OR=1.68, 95% CI=1.26–2.25), tumor differentiation (OR=1.90, 95% CI=1.25–2.88) and TNM stage (OR=1.66, 95% CI=1.25-2.20)." (PMID 29088887, 2017). "Taken together, high TACC3 expression may increase the aggressiveness of tumor cells by increasing their invasive capacities, stem cell-like properties, and antiapoptotic activities." (PMID 29135996, 2017). "Knockdown of TACC3 can improve the sensitivity of tumor cells to chemotherapeutic drugs by effectively regulating premature senescence, and this suggests that TACC3 may be a potential biomarker for monitoring the efficacy of chemotherapy." (PMID 29088887, 2017). "Functions’ annotations and gene sets’ enrichment analysis suggested that TACC3 may participate in cell cycle, DNA repair, epithelium-mesenchymal transition and other tumor-related biological processes and molecular pathways." (PMID 28273854, 2017). "In summary, our data indicate that knockdown of TACC3 repressed tumour growth in nude mice." (PMID 27248823, 2016). "Recently, various reports have suggested that TACC3 may be a potential therapeutic target and that the targeted knockdown of TACC3 can inhibit tumor cell proliferation and induce apoptosis." (PMID 27705912, 2016). "Another study demonstrated that TACC3 suppression causes tumor regression and leads to embryonic lethality in mice due to massive apoptosis in tumor, but not normal, tissues." (PMID 27705912, 2016). "Additionally, high TACC3 expression was positively correlated with poor differentiation, microvascular invasion, and, in particular, tumor size." (PMID 26219398, 2015). "Interestingly, TACC3 expression in each tumor tissue was higher than that of the corresponding matched non-tumor tissue." (PMID 25760075, 2015). "Taken together, these data demonstrated that TACC3 expression was increased in HCC tumor tissues." (PMID 26219398, 2015). "Tumor size showed the most significant correlation with TACC3 expression (p < 0.001)." (PMID 26219398, 2015). "For example, increases in Tacc3 and Aurora A kinase (Aurka) can produce tumor like cells." (PMID 22312355, 2011). "Similarly, focal gains at 4p16, most commonly involving TACC3, and overexpression of TACC3 were found in tumor samples, raising the possibility of TACC3 as a potential GBM oncogene." (PMID 21304175, 2010). "TACC3 was found to be up-regulated in both tumour cell lines." (PMID 18544163, 2008). "Furthermore, correlation analysis with immune genes revealed a positive correlation between TACC3 and several immune checkpoint genes, suggesting coordinated expression of these genes in various signaling pathways, thereby impacting tumor response to immunotherapy." (PMID 39603208, 2025). "These two distinct tumor types might display FGFR3::TACC3 fusion." (PMID 36647073, 2023). "Furthermore, TACC3 levels were significantly related to tumor histological type (P = 0.006), nerve invasion (P = 0.003), differentiation (P = 0.004), surgical margin (P = 0.012), parametrium invasion (P = 0.040), P16 expression (P < 0.001), and Ki-67 (P = 0.004)." (PMID 34134633, 2021). "These datas suggest that TACC3 overexpression may contribute to tumor progression." (PMID 34134633, 2021). "Together, these studies suggest that TACC3 may play an important role in tumor progression." (PMID 33714201, 2021). "In addition to its role in mitosis, TACC3 has been proved to promote tumor growth." (PMID 29088887, 2017).
tumor (continued). "Secondly, the increased frequency of rs798766[T] may accelerate the tumor formation through upregulating the expression of TACC3 which increases the microtubule dynamic stability and massively promotes cell division, possibly enhanced by simultaneously stimulated FGFR3 activation." (PMID 28655970, 2017). "Therefore, the targeted silencing of TACC3 may be a valid approach for anti-tumor therapy for CCA; however, its mechanism still needs further experimental exploration." (PMID 27705912, 2016). "Thus, patients with a high level of TACC3 expression could be recommended to receive aggressive radiotherapy and chemotherapy to reduce tumour malignancy and metastasis." (PMID 27248823, 2016). "Therefore, targeted TACC3 silencing may be a valid approach for anti-tumor therapy for patients with CCA." (PMID 27705912, 2016). "Thus, tracking the status of TACC3 levels may also offer an opportunity for monitoring tumor progression and metastasis." (PMID 26682275, 2015). "This fusion involves fibroblast growth factor receptor 3 (FGFR3) and transforming acidic coiled-coil containing protein 3 (TACC3), leading to the constitutive activation of oncogenic signaling pathways that promote tumor growth and progression." (PMID 40417325, 2025). "Most reports describe FGFR3::TACC3 as an acquired event after EGFR-TKI therapy, and its presence in a TKI-naïve tumor suggests a potential de novo co-activation of independent oncogenic pathways." (PMID 41301039, 2025). "Knockdown of TACC3 leads to abnormal spindle formation and S phase arrest during PDAC cell division, which inhibits tumor cell proliferation." (PMID 38012214, 2023). "Knockdown of TACC3 and its downstream protein KIF11 inhibits tumor cell proliferation and increases chemosensitivity in PDAC." (PMID 38012214, 2023). "The results of this research enhance our comprehension of the potential positive influence of TACC3 in LUAD and illuminate a potential correlation and probable mechanism between TACC3 and tumor-immune interplay." (PMID 35855850, 2022). "Premised on the median TACC3 expression value, we accessed 438 LUAD tumor tissues from the TCGA and categorized them into low and high expression cohorts." (PMID 35855850, 2022). "To explore the role of TACC3 in tumor microenvironment (TME) immune mechanisms and immune responses, we analyzed the correlation between TACC3 expression and TMB and MSI." (PMID 35855850, 2022). "Cox regression analysis indicated that TACC3 expression is a prognostic factor, along with age, FIGO stage, tumor size, histologic type, stromal invasion, nerve invasion, LVI, LNM, parametrium invasion, surgical margin, and P16 expression." (PMID 34134633, 2021). "To further elucidate the intrinsic relationship between tumor infiltrating immune cells and TACC3 expression in KIRC, we detected the expression signatures of 12 immune cell subtypes in low and high TACC3-expressing tumors." (PMID 33714201, 2021). "It is noteworthy that activation of the MAPK/ERK and PI3K/Akt pathways is an important step required for EMT process induced by various tumor-related factors including TGF-β, TACC3, EGF, BMP7, ZNF143, and CXCR4 26-31." (PMID 31417642, 2019). "First, overexpression of TACC3 promotes the PI3K/AKT and ERK signaling pathways that induce epithelial-mesenchymal transition, which enhances the migratory ability of tumor cells and increases their invasive capacity." (PMID 29135996, 2017). "Fibroblast growth factor receptor 3-transforming acidic coiled-coil-containing protein 3 (FGFR3-TACC3) fusion transcript is recurrently detected in HNSCC and has been shown to play a key role in tumor resistance." (PMID 28030848, 2017). "Our results demonstrated that knock down of TACC3 reduced CRC cell proliferation, clonogenicity, migration and invasion capability, as well as tumour growth in nude mice." (PMID 27248823, 2016). "In addition to the EMT, TACC3 may also affect tumor stem cell-like capabilities." (PMID 26219398, 2015).
tumor (continued). "However, whether TACC3 acts as a tumor suppressor or an oncogene was controversial among studies." (PMID 25760075, 2015). "These three tumors are suggestive of a potential tumor entity driven by the FGFR3::TACC3 fusion and lacking HPV infection, which merits further delineation in the future when more cases are reported." (PMID 39387893, 2025). "Consistently, initial IHC analysis of conventional sections revealed significantly greater TACC3 expression in tumor tissues than in adjacent nontumor tissues." (PMID 40866361, 2025). "CCK-8 assays confirmed that GalNAc–siTACC3 failed to suppress tumor cell viability in TACC3-knockout Hepa1‒6 cells, establishing its dependence on intact TACC3 expression." (PMID 40866361, 2025). "That fusion-positive case, which has been reported as SDC, harbored additional driver alterations (BRCA2 and PTEN) in addition to the FGFR3::TACC3 fusion; the morphology of the tumor has not been illustrated." (PMID 39387893, 2025). "To test the effects of TACC3 knockout on in vivo tumor growth, we injected sgCtrl vs. sgTACC3-expressing JIMT-1 and MDA-MB-231 cells to the mammary fat pad (MFP) of nude mice and monitored tumor growth." (PMID 36864125, 2023). "Transforming acidic coiled-coil-containing protein 3 (TACC3) is a component of the centrosome axis and a member of the TACC family, which affect mitosis and regulate chromosome stability and are involved in tumor development and progression." (PMID 38012214, 2023). "In addition, we tested the effects of pharmacological inhibition of TACC3 on tumor growth in both MDA-MB-231 xenografts and the TNBC PDX, TM01278 with CA using the TACC3 inhibitor, BO-264." (PMID 36864125, 2023). "Conversely, TACC3 knockdown inactivates PI3K/AKT signaling in KIRC cells, suggesting that PI3K/AKT signaling may be involved in tumor growth." (PMID 33714201, 2021). "TACC3 mRNA levels (95.2%, 21/23) were also elevated in the tumor tissues compared with the counterpart non-cancerous tissues." (PMID 26219398, 2015). "Previously, we demonstrated that TACC3 plays a pivotal role in the process of epithelial-mesenchymal transition (EMT), a key step of tumor progression and metastasis, by promoting phosphoinositide 3-kinase (PI3K)/Akt and extracellular signaling related kinase (ERK) signaling." (PMID 26682275, 2015). "To investigate whether reducing TACC3 protein expression in PDAC can inhibit tumor progression, we constructed a mouse subcutaneous tumor model with Panc-1 cells and treated the mice daily with a concentration gradient of MCT, 15 mg/kg KHS101, or 30 mg/kg KHS101." (PMID 38012214, 2023). "Notably, targeting TACC3 using genomic knockout or pharmacologic inhibition strongly inhibited tumor growth without any observable toxicity in cell line or patient-derived xenografts with CA." (PMID 36864125, 2023). "Therefore, it is of interest to determine whether TACC3 is involved in ECA cell differentiation and proliferation.Several studies have attempted to examine the role of TACC3 in tumor development." (PMID 34134633, 2021). "In addition, TACC3 expression demonstrated a significant negative correlation with tumor purity in KIRC (cor = -0.243, p = 1.21e-07)." (PMID 33714201, 2021). "Our analysis revealed that TACC3 expression significantly correlated with 88.1% (37/42) of the immune markers identified in KIRC, which validated the results of our previous analyses and further suggested that TACC3 plays a significant role in tumor immune infiltration (p < 0.05)." (PMID 33714201, 2021). "Tumor tissues had a more abundant level of TACC3 mRNA than the normal epithelium." (PMID 29358577, 2018).